IFNG (interferon gamma)
Diseases named in the same sentence as IFNG in open-access papers (continued):
Sharing a sentence is not in itself a finding about the gene and the disease.
Cognitive impairment (45 papers, 2013 to 2026). Abnormal cognition is characterized by deficits in thinking, reasoning, or remembering. "In a mouse model of endotoxemia and associated cognitive impairment, IFNγ levels increased in plasma and CSF, a finding that was consistent with the results collected from human patients with sepsis." (PMID 36915214, 2023). "In the LPS-treated mice, IFNγ signaling was pronounced in the hippocampus and was associated with reduced neurogenesis and increased cognitive impairment." (PMID 36915214, 2023). "Of note, there were also elevated levels of IL-10, IFNγ, and sTREM2 in long-COVID patients, especially in the group suffering from cognitive impairment." (PMID 39799217, 2025). "Interferon-γ (IFNγ) is a pro-inflammatory cytokine whose production is altered in many conditions displaying some degree of cognitive deficits, although its role in cognitive functioning is still unclear." (PMID 26731444, 2016). "Interferon-gamma(IFN-γ) The activation of microglia damages the neurogenesis of adult hippocampus and leads to depressive behavior and cognitive impairment." (PMID 37065890, 2023). "Compared with healthy controls, differentiated CD3+ T-cells is increased in AD hippocampal parenchyma, and activated T cells generate interferon gamma (IFN-α) that can result in the deposition of Aβ, cognitive impairment, and subsequently AD." (PMID 35139899, 2022). "The decision of choosing IFNγ to stimulate CHME3 microglia was supported by the involvement of this cytokine in AD pathology, reported in both mild- and severe-stage patients compared to individuals with mild cognitive impairment (MCI)." (PMID 35620289, 2022).
liver disease (45 papers, 2011 to 2025). "IFNγ is associated with hepatic inflammation in patients with liver diseases." (PMID 38907339, 2024). "Of note, IFNγ production by ascites CD8+ T cells correlated with markers of liver disease severity, and this was also true for the CXCR6+CD69+ CD8+ T-cell subset." (PMID 38882602, 2024). "IFNγ production by the CD49a- NK cell populations was comparable between the two liver disease groups (p > 0.05)." (PMID 31803181, 2019). "TNFα and IFNγ are known to be significantly up‐regulated in inflammatory liver disease and important activators of endothelium during cellular injury." (PMID 27770554, 2017). "Notably, the dataset includes many known proteins (IL6, IL10, IFNG, CSF3, PDGFB, CD40, and AFP) and novel proteins associated with liver diseases." (PMID 37209815, 2023). "However, the impact of IFNγ on the murine models of liver diseases is controversial." (PMID 38907339, 2024). "Of note, baseline expression of IFNγ and TNFα appeared to be similar in CD8+ T cells of patients across all stages of liver disease compared with healthy controls." (PMID 41028194, 2025). "This was further corroborated by correlations of IFNγ production of peritoneal CD8+ T cells and peritoneal CXCR6+CD69+ CD8+ T cells with markers of liver disease severity and renal impairment." (PMID 38882602, 2024). "The clonal expansion of CD4+ T cells leads to cytokine release (IL-2, IL-10, IFNγ), which stimulates the immune-mediated killing of HDV-infected cells but in an unregulated manner, which also leads to liver necrosis and progressive liver disease." (PMID 35267563, 2022). "Here, Tregs suppress not only the production of interferon gamma (IFNγ) but also the expansion and activation-induced cell death of HCV-specific T cells resulting in reduced CD4+ T cell reactivity and mitigation of T cell-mediated liver disease." (PMID 34691057, 2021). "We found that STAT4 was constitutively phosphorylated to greater levels in PBC than in the liver disease controls, and of functional relevance NK cells in PBC could be induced to secrete more IFNγ." (PMID 31803181, 2019). "It is probable that increased cellular accumulation and the elevated production of inflammatory mediators such as IFNγ and CXCL9 as well as others not evaluated by this study accounts for the extent of liver disease in observed IL-10 deficient livers." (PMID 22880122, 2012). "Therefore, although predominantly M1, here we confirm the coexistence of both M1 and M2 phenotypes among CD14+ blood monocytes stimulated with LPS/IFNγ in our model of EADs without advanced liver disease." (PMID 37760011, 2023). "The percentage of differentiated Th cells by APCs in the experimental models of liver disease was significantly reduced with the norfloxacin treatment in the CCl4 model, whereas it didn’t induce significant changes in the BDL model, except for IFNg and IL-17 by LSECs." (PMID 32429209, 2020).
renal cell carcinoma (45 papers, 2000 to 2026). "IL-12 mediated by Ad5-ZD55-hCCL5-hIL12 also induced the phosphorylation of Stat4 in CAR-T cells, thereby promoting an increased secretion of interferon-gamma (IFN-γ) by these cells in renal cell carcinoma." (PMID 40821119, 2025). "Another gene, interferon gamma (IFNG), is significantly associated with CD8+ T cell infiltration in renal cell carcinoma." (PMID 37600792, 2023). "Interferon-gamma (IFN-γ) has a complex role in modulating the tumor microenvironment (TME) during renal cell carcinoma (RCC) development." (PMID 34795663, 2021). "Furthermore, IL-12 administration preferentially increased hepatic T cell activation and IFNγ expression in the RENCA mouse model of renal cell carcinoma." (PMID 22428016, 2012). "CCL22, CRP, ICAM1, IFNG, PDGFRA, TGFB1 and TNFSF11 have been confirmed to be involved in the malignant progression and metastasis of renal cell carcinoma through different biological mechanisms." (PMID 34187413, 2021). "Human primary gastric, colon and renal cell carcinomas were shown to constitutively express both IDO1 and IDO2 mRNA, whereas cancer cell lines generally required induction of IDO by interferon-gamma (IFNγ)." (PMID 26378585, 2015). "Relevant study also demonstrated that co-administration of targeted TNFα and nontargeted IFNγ resulted in significant synergistic tumoricidal activity in renal cell carcinoma." (PMID 27342639, 2016). "Targeted TNFα and nontargeted IFNγ exerted additive tumoricial activity in renal cell carcinoma." (PMID 27342639, 2016). "In melanomas, renal cell carcinomas (RCC) and squamous cell carcinomas of the head and neck (SCCHN), phosphorylated STAT1, and not STAT3, is involved in IFNγ-triggered PD-L1 transcription." (PMID 35402280, 2022).
abortion (44 papers, 2005 to 2025). the ending of pregnancy by removing a fetus or embryo before it can survive outside the uterus. "It was reported that abortion is associated with infiltrations of CD4+ T cells and NK cells and the subsequent production of IFNG in the placenta." (PMID 40872670, 2025). "To determine whether tregitope treatment restores the Th1/Th2 balance during pregnancy in abortion-prone mice, we examined the levels of IL-2, IL-4, IL-10, IFNγ and TGFβ1 cytokines in blood sera." (PMID 32601347, 2020).
allergic rhinitis (44 papers, 2009 to 2026). Inflammation of the nasal mucous membranes caused by an IgE-mediated response to external allergens. "Exposure to PM2.5 exacerbates allergic rhinitis in mice by increasing DNA methylation of the interferon-gamma gene promoter in CD4+ T cells via the extracellular signal-regulated kinase-DNA methyltransferase pathway." (PMID 35378908, 2022). "In another in vivo study on balb/c mice, DAP showed anti-inflammatory effects on ovalbumin-induced allergic rhinitis via reducing serum levels of IgE, IL-4, and IFNγ as well as decreased number of mucosal eosinophils and pathological changes in respiratory epithelial." (PMID 35949308, 2022).
chronic obstructive pulmonary disease (44 papers, 2004 to 2026). A chronic and progressive lung disorder characterized by the loss of elasticity of the bronchial tree and the air sacs, destruction of the air sacs wall, thickening of the bronchial wall, and mucous accumulation in the bronchial tree. "We demonstrate that alveolar macrophages display high resemblance to IL10 activation, but show a drop in IFNγ signature in chronic obstructive pulmonary disease patients." (PMID 31921150, 2019). "Increased interferon gamma (IFNγ) release occurs in Chronic Obstructive Pulmonary Disease (COPD) lungs." (PMID 28830544, 2017). "In viral infections and patients with chronic obstructive pulmonary disease (COPD), ILC2s have been documented to convert to an ILC1-like phenotype characterised by T-bet expression and IFNg production in response to the cytokines IL-1b, IL-12 and IL-18." (PMID 38745765, 2024). "In ASMC from people with chronic obstructive pulmonary disease (COPD), TNF-α induced CXCL10 via NF-κB activation, whereas IFNγ only induced a weak activation of NF-κB and activated STAT-1 as well, but not AP-1." (PMID 23034049, 2012).
head and neck squamous cell carcinoma (44 papers, 2009 to 2026). A squamous cell carcinoma that arises from any of the following anatomic sites: lip and oral cavity, nasal cavity, paranasal sinuses, pharynx, larynx, and salivary glands. "APOBEC mutations are associated with inflammation-related interferon-gamma gene expression signature in head and neck squamous cell carcinoma." (PMID 38711096, 2024). "SN-38 has also been proven to enhance anti-tumor immunity by increasing interferon-gamma expression by natural killer (NK) cells and promoting NK and T-cell infiltration in mouse tumor models of head and neck squamous cell carcinoma." (PMID 40244130, 2025). "Examples include increased IFNγ infiltration observed in head and neck squamous cell carcinoma (HNSCC) preclinical models treated with a TGFβ inhibitor-expressing VV, making the tumor more responsive to treatment." (PMID 40709190, 2025). "Using specific inhibitors, we identified a potential role for IDO as apoptotic mediator in the regulation of IFNγ-induced apoptosis of head and neck squamous cell carcinoma (HNSCC) cells via Noxa-mediated mitochondrial dysregulation and ER stress." (PMID 27486476, 2016). "Compared with TIDE, MIS score, CD8, IFNG, and Merck18, DDX20 alone had a higher AUC (0.62) in head and neck squamous cell carcinoma (Uppaluri2020_PD1_HNSC_Post)." (PMID 36246406, 2022). "Compared with TIDE, MIS score, CD274, CD8, IFNG, and Merck18, DDX20 alone had a higher AUC (0.71) in head and neck squamous cell carcinoma (Uppaluri2020_PD1_HNSC_Pre)." (PMID 36246406, 2022). "Moreover, targeting TLR3 enabled NK cells to kill head and neck squamous cell carcinoma (HNSCC) by secreting IFNγ." (PMID 34124272, 2021). "Similarly, intratumoral injection of recombinant human IL-12 in patients with head and neck squamous cell carcinoma (HNSCC) showed increased NK cells and IFNγ expression in the tumors and lymph nodes compared to the control arm, which correlated to the overall survival." (PMID 35401529, 2022). "Interferon-gamma (IFNG) plays a key role in immune responses in head and neck squamous cell carcinoma (HNSCC) and impacts the effectiveness of immune checkpoint inhibitors." (PMID 41368643, 2025).
hepatitis B (44 papers, 2006 to 2025). "IFNγ promoted hepatic inflammation in the transgenic mice model of hepatitis B, acetaminophen-induced ALI, and Con A-induced ALI." (PMID 38907339, 2024). "In the acute phase of the disease, CTLs contribute immunopathological effects of hepatitis B by producing cytokines, such as IFNγ and cytotoxic activity." (PMID 36411916, 2022). "The hepatic infiltration of IFNγ positive lymphocytes was related to the inflammatory process in chronic hepatitis B patients, and IFNγ positive peripheral blood mononuclear cells (PBMCs) increased in acute exacerbation of hepatitis B." (PMID 38907339, 2024). "IL-2 and IFNγ release in this assay depicts hepatitis B vaccination status." (PMID 30602374, 2019). "For example, COX-2 inhibition in VSV-infected mice increases plasma IFNγ and IL-12 levels, and treatment of hepatitis B or C patients with the COX-1/COX-2 inhibitor indomethacin increases serum levels of the IFN response product 2′5′-oligoadenylate synthetase-1." (PMID 23850620, 2013). "In agreement with our data, a recent work analyzing immunological response to Hepatitis B vaccination in treated HIV infection, has shown that IFNγ secretion by CD8+ T cells after Hepatitis B-specific stimulation is significantly increased in responders only." (PMID 29444185, 2018). "Regarding hepatitis B infection, CD8T cells producing interferon gamma and tumor necrosis factor (TNF)-α may influence regulatory T lymphocytes, altering the Th1/Th2 balance." (PMID 40191527, 2025). "Since HBsAg is a main component of the prophylactic hepatitis B vaccine it does not surprise that the HBsAg-mediated production of the cytokines IL-2 and IFNγ correlates with the blood donors’ vaccination status as published previously." (PMID 30602374, 2019). "Seventy two chronic Hepatitis B patients (CHB), 8 acute hepatitis B patients (AHB) and 80 healthy controls (HC) were tested by ELISA for IFNγ- and IL2-secretion in whole blood after challenge with synthetic peptide libraries of hepatitis B core antigen (HBcAg) or hepatitis B surface antigen (HBsAg)." (PMID 25968473, 2015).
mastitis (44 papers, 2009 to 2025). Inflammation of breast tissue during lactation or postpartum due to an obstructed duct or infection. "This study looks at expressions of genes, such as IL-4, IL-10, and IFNγ, linked to immune response mechanisms in mastitis." (PMID 35445115, 2022). "In addition, IFNG, IL–6, and IL–1β are also associated with at least two mint components, demonstrating that the treatment of mastitis in dairy cows with mint is the result of the synergistic action of multiple components." (PMID 40005889, 2025). "In the frame of mastitis in ruminants and mice models, it has been reported that staphylococci and streptococci involved in CM cases are inhibited by the highly expressed IFNγ that is produced as a response to the infection." (PMID 39896819, 2024). "In cows with mastitis, the expressions of IL-4 and IFNγ genes were significantly lower than those in healthy animals (p < 0.0001)." (PMID 35445115, 2022). "Compared to cows infected with clinical mastitis, healthy cows had higher expression of IL-4 and IFNγ genes (p < 0.0001)." (PMID 35445115, 2022). "Compared to cows diagnosed with clinical mastitis, the IL-4 and IFNγ genes were expressed more strongly in healthy cows (p> < 0.0001)." (PMID 35445115, 2022). "The expressions of IL-10, IL-4, and IFNγ genes were contrasted in mastitis-free and mastitis-affected animals." (PMID 35445115, 2022). "Inflammatory cytokine interleukin (IL-10), IL-4, and interferon-gamma (IFNγ) expression genes were measured and compared in mastitis-free and mastitis-affected animals." (PMID 35445115, 2022). "IL-10, and IFNγ genes were differentially expressed in mastitis and healthy conditions (p ˂ 0.01), indicating that these genes are strong indicators of mastitis in the conditions studied." (PMID 35445115, 2022). "These genes are strong predictors of mastitis in the states analyzed, as evidenced by the differential expression in mastitis and healthy conditions of the IL-4, IL-10, and IFNγ genes." (PMID 35445115, 2022). "Interferon-gamma has been used to manage acute bovine mastitis during the periparturient period." (PMID 40936092, 2025). "In addition, the anti-mastitis capability of human IFNγ has been confirmed in transgenic goat mammary gland epithelial cells." (PMID 39896819, 2024). "Mastitis caused by Gram-positive and Gram-negative bacteria was used to assess the expressions of IL-4, IL-10, and IFNγ genetic features connected to the immune system response pathways to mastitis." (PMID 35445115, 2022). "Utilizing the PPI network, the topological parameters of Betweenness unDir, Closeness unDir, and Degree unDir were employed to predict the core targets for mint in treating mastitis in dairy cows, which include TNF, IL–6, STAT–3, IL–1β, FGF–2, IFNG, and ESR–1." (PMID 40005889, 2025). "Our study showed that the mastitis immunological profile in the mammary gland may be related to specific HMOs, as the levels of the branched hexasaccharide LNH, its disialylated derivative DSLNH, 3’SL, and DFLac were positively associated to some pro-inflammatory cytokines (IL2, IL6, IL17 and IFNγ)." (PMID 35079053, 2022). "Comparison of the relative gene expressions of IL-10, IL-4, and IFNγ in animals with and without mastitis and the respective significance level of the means." (PMID 35445115, 2022). "During the process of mastitis pathogenesis, the production of pro-inflammatory cytokines is acutely induced to activate immune responses: firstly IL-8 attracts neutrophils, followed by TNF-α, interferon gamma (IFN-γ), and IL-1β induces tissue inflammation." (PMID 34827927, 2021). "For this purpose, the expression of the interleukin 2 (IL-2), IL-4, IL-6, IL-8, IL-10, interferon gamma (IFN-γ) and tumor necrosis factor alpha (TNF-α) genes was investigated in Black and White (BW) Holstein and Gyr cows with and without clinical signs of mastitis." (PMID 21637453, 2009).
alopecia areata (43 papers, 2010 to 2026). Loss of scalp and body hair involving microscopically inflammatory patchy areas. "Not surprisingly, a majority of studies exploring the serum expression of Th1 cytokines have demonstrated an increase in the Th1 hallmark cytokine IFNγ, and IFNγ-induced collapse of hair follicle immune privilege has been described as a key element in the pathogenesis of alopecia areata." (PMID 37759685, 2023). "IFNγ-mediated STAT1 activation is also implicated in the pathogenesis of hidradenitis suppurativa and alopecia areata." (PMID 39161766, 2024). "The systemic inflammatory profile of alopecia areata (AA) regarding IFNγ and Th1 cytokine dysregulation has previously been described, suggesting an increased incidence of CVDs in this population." (PMID 39064304, 2024). "In terms of HF pathophysiology, lesional alopecia areata skin has been shown to have increased levels of IFNγ mRNA and IFNγ has potent catagen (HF regression) promoting effects." (PMID 23626671, 2013). "In the initial phases of alopecia areata, the overproduction of interferon-gamma (IFN-γ) induces the expression of major histocompatibility complex (MHC) class I in hair follicles by upregulating chemokines of the C-X-C motif (CXCL) and intracellular adhesion molecules (ICAM)." (PMID 39768634, 2024). "Alopecia areata is considered a type 1 inflammatory disease, where activated NKG2D+CD8+ cells produce the Th1 cytokine interferon-gamma." (PMID 38903518, 2024). "In animal experiments, it is found that IFN-γ-driven immune response, including IFNγ, IFNγ-induced chemokines, and cytotoxic CD8+ T cells are important mechanisms leading to alopecia areata." (PMID 34196345, 2021). "However, numerous studies indicate that alopecia areata is associated with a systemic immune activation and the dysregulation of multiple proinflammatory cytokines, including Interleukin 1 beta (IL-1β), IL-6, tumor necrosis factor alpha (TNF-α), and interferon gamma (IFN-γ)." (PMID 34830700, 2021).